IDH2 (isocitrate dehydrogenase (NADP(+)) 2)
Diseases named in the same sentence as IDH2 in open-access papers (continued):
Sharing a sentence is not in itself a finding about the gene and the disease.
glioma (continued). "Using the EPIC methylation array, which is a more robust array covering > 850,000 CpG sites, and a discovery cohort of 39 glioma tissue samples, we successfully developed a DNA methylation (CIMP) signature to specifically distinguish IDH1/IDH2-positive samples from IDH1/IDH2-negative samples." (PMID 36360312, 2022). "However, recent human clinical data in IDH1 and IDH2 mutant AML, where not all mutant patients respond to inhibitor treatment, points to the plausibility that not all mutant glioma patients will respond to such therapy." (PMID 29062039, 2017). "As clearly demonstrated by the examples of gliomas and AML with the oncogenic metabolite d-2-hydroxyglutarate, the establishment of RCG, even concomitantly with OXPHOS glutaminolysis (note that this mode does not require IDH2 and aconitase reactions), helps to accelerate the malignant phenotype." (PMID 22675360, 2012).
acute myeloid leukemia (283 papers, 2010 to 2026). Acute myeloid leukemia (AML) is a group of neoplasms arising from precursor cells committed to the myeloid cell-line differentiation. "In humans, IDH1 and IDH2 mutations are frequently observed in cancers such as gliomas and acute myeloid leukemia (AML)." (PMID 39941051, 2025). "The efficacy of enasidenib in the treatment of relapsed or refractory acute myeloid leukemia AML with IDH2 mutations was assessed by the ORR, and it was found that enasidenib significantly prolonged patient survival." (PMID 40696413, 2025). "Mutations in IDH1 or IDH2, present in ∼15–20% of acute myeloid leukemia (AML) cases, generate the oncometabolite (R)-2-hydroxyglutarate (2-HG), enforcing a hypermethylated, differentiation-refractory state." (PMID 41347170, 2025). "Enasidenib is an inhibitor that targets IDH2, distinct from ivosidenib above, and is intended primarily as a therapeutic agent for acute myeloid leukemia with IDH2 mutations." (PMID 40696413, 2025). "Some studies have shown that the IDH2 inhibitor endesipine can be used to treat relapsed or refractory acute myelogenous leukemia carrying IDH2 mutations." (PMID 41256322, 2025). "It is currently known that IDH1 or IDH2 mutations are present in 8% and 12%, respectively, of acute myeloid leukemias." (PMID 40017726, 2025). "For instance, the abnormal activation of PI3K/AKT, mTORC1, ERK/MAPK, STAT3/5, IDH2, Wnt/β-catenin, and NF-κB pathways are linked to the relapse and pathogenesis of cancer such as acute myeloid leukemia." (PMID 40017726, 2025). "For anticancer drugs, ivosidenib and enasidenib were developed on the basis of oncometabolites, which inhibit mutated IDH1 and mutated IDH2, respectively, in acute myeloid leukemia (AML), thereby suppressing the biosynthesis of D-2-hydroxyglutarate." (PMID 38468344, 2024). "Acute myeloid leukemia with mutations in TET2 or IDH2 is sensitive to epigenetic therapy involving the inhibition of DNA methyltransferase activity using 5-azacytidine or the inhibition of mutant IDH2." (PMID 38929174, 2024). "IDH1 and IDH2 are recurrently mutated in myeloid neoplasms, including myelodysplastic syndrome (5%‒10%), acute myeloid leukemia (10%‒20%), and MPN (1%‒5%), as well as in lymphoma and some solid cancers." (PMID 39157630, 2024). "The potential of enasidenib needs to be underscored as it is already clinically used for patients with IDH2-mutated relapsed/refractory acute myeloid leukemia (AML)." (PMID 38987856, 2024). "An analysis of transcriptomes from 982 acute myeloid leukemia patients showed that RNA variants in isocitrate dehydrogenase (NADP(+)) 2 (IDH2) and serine- and arginine-rich splicing factor 2 (SRSF2) promoted leukemogenesis and epigenome and RNA splicing." (PMID 39408729, 2024). "Non-driver mutations, such as those in ASXL1, EZH2, TET2, SRSF2, and IDH1/IDH2, have been found to exacerbate disease severity, accelerate progression, and increase the risk of transformation to acute myeloid leukemia (AML)." (PMID 39434124, 2024). "IDH1 and IDH2 mutations have been described in different types of cancer, including glioblastoma, and are being targeted for acute myeloid leukaemia." (PMID 36880517, 2023). "Mutations in IDH1 and IDH2 genes lead to increased production of D-2 hydroxy-glutarate (2HG), contributing to the development of various malignancies such as acute myeloid leukemia, chondrosarcoma, cholangiocarcinoma, and glioma." (PMID 36902385, 2023). "Preclinically, enasidenib and azacitidine (ENA + AZA) synergistically enhance cell differentiation, and venetoclax (VEN), a small molecule Bcl2 inhibitor (i) is particularly effective in IDH2 mutated acute myeloid leukemia (IDH2mutAML)." (PMID 35078972, 2022). "Ivosidenib (AG-120) is an oral inhibitor of the IDH1 mutated enzyme, while enasidenib (AG-221) inhibits mutated IDH2; both are approved for the treatment of acute myeloid leukaemia (AML)." (PMID 35267432, 2022).
acute myeloid leukemia (continued). "Heterozygous somatic mutations affecting IDH1/IDH2 genes and DNA methylation profiles have also been found in glioma and acute myeloid leukemia (AML)." (PMID 35269864, 2022). "Two IDH inhibitors, Enasidenib and Ivosidenib, have been approved by the FDA for the treatment of patients with refractory or relapsed acute myeloid leukemia (AML) bearing IDH2 mutations." (PMID 35806153, 2022). "Ivosidenib, an inhibitor of IDH1 mutants, and enasidenib, an inhibitor of IDH2 mutants, are reportedly effective against relapsed and refractory acute myeloid leukaemia (AML) with IDH1 and IDH2 mutations, respectively." (PMID 33562094, 2021). "IDH2 protein mutants causing elevated 2HG are known to occur in several malignancies, including acute myeloid leukemia and AITL." (PMID 34771688, 2021). "AG-221, a first-in-class therapy targeting acute myeloid leukemia (AML) harboring oncogenic IDH2 mutations, suppress the 2-HG production and induce cellular differentiation in primary human IDH2 mutation-positive AML cells in vitro and vivo." (PMID 35006438, 2021). "Enasidenib has been approved on 1 August 2017 for the treatment of adult relapsed/refractory acute myeloid leukemia (R/R AML) with IDH2 mutations." (PMID 33688498, 2021). "Enasidenib was granted regulatory approval by the FDA on 1 August 2017 for the treatment of adult patients with relapsed or refractory acute myeloid leukemia with an isocitrate dehydrogenase-2 (IDH2) mutation as detected by an FDA-approved test." (PMID 34200553, 2021). "IDH1 and IDH2 mutations (IDH1/2Mut) are recognized as recurrent genetic alterations in acute myeloid leukemia (AML) and associated with both clinical impact and therapeutic opportunity due to the recent development of specific IDH1/2Mut inhibitors." (PMID 33941203, 2021). "IDH2 mutation was most common in acute myeloid leukemia (11%), followed by <6% in cholangiocarcinoma; however, IDH2 amplification was more common, albeit at low frequencies, among various cancer types." (PMID 34440884, 2021). "The initial mutations identified were IDH1 and IDH2 in ~ 80% of intermediate grade gliomas and in ~ 20% of de novo acute myeloid leukemia." (PMID 33413208, 2021). "Mutations in IDH1 and IDH2 genes have been described in several malignancies, including gliomas, acute myeloid leukemia (AML), and myelodysplastic disorders." (PMID 34069269, 2021). "Mutations in IDH2 have been first reported in glioblastoma multiforme, next in acute myeloid leukemia, and other malignancies such as breast invasive ductal carcinoma, colon adenocarcinoma, lung adenocarcinoma, and oligodendroglioma." (PMID 34641967, 2021). "IDH1 and IDH2 mutations are present across several cancers including in 5-16% and 6-19% of acute myeloid leukaemia (AML), respectively." (PMID 33391954, 2021). "Multiple mutations in IDH isoenzymes IDH1 and IDH2, which normally catalyze oxidative decarboxylation of isocitrate to α-KG, have been shown to occur frequently in gliomas and acute myeloid leukemia." (PMID 32252351, 2020). "For example, enasidenib is a selective IDH2 inhibitor, which is in early phase clinical trials for patients with acute myeloid leukaemia, a disease which commonly harbours IDH-2 mutations." (PMID 31819180, 2020). "Other studies showed that somatic mutations in IDH2 (R172 and R140) also increased the D2-HG levels in acute myelogenous leukemia (AML)." (PMID 32993063, 2020). "IDH1 mutations involving codon 132 and IDH2 mutations involving codons 140 and 172 occur in a variety of human cancers, including acute myeloid leukemia (AML), diffuse gliomas, cholangiocarcinoma, and chondrosarcoma." (PMID 32333643, 2020). "Mutations in IDH1 and IDH2 have been observed in tumors such as acute myelogenous leukemia (AML), grade II-III glioblastoma, chondrosarcoma and have been implied in promoting tumorigenesis by altering DNA and histone methylation status." (PMID 30283496, 2018).
acute myeloid leukemia (continued). "Acute myeloid leukemia is a complex hematologic malignancy that is driven by multiple genetic mutations, including isocitrate dehydrogenase 2 (IDH2; Medinger & Passweg, 2017)." (PMID 30719396, 2018). "Mutations of the isocitrate dehydrogenase genes (IDH1 and IDH2) have been detected in several tumor types including chondrosarcoma, acute myeloid leukemia (AML), cholangiocarcinoma and diffuse glioma." (PMID 29499756, 2018). "IDH1 and IDH2 mutations have been identified in acute myelogenous leukemia, lymphoma, glioblastoma, chondrosarcoma and other solid tumours." (PMID 30356832, 2018). "Mutations of isocitrate dehydrogenase 1 (IDH1) and IDH2 in acute myeloid leukemia (AML) cells produce the oncometabolite R-2-hydroxyglutarate (R-2HG) to induce epigenetic alteration and block hematopoietic differentiation." (PMID 27577048, 2016). "The extent of intron retention correlated with the presence of IDH1 and IDH2 mutations in acute myeloid leukemia and across molecular subtypes in breast cancer." (PMID 26113877, 2015). "Isocitrate dehydrogenase 1 (IDH1), and IDH2 mutations were originally reported as frequent events in gliomas and acute myeloid leukaemia." (PMID 25432631, 2015). "The isocitrate dehydrogenase (IDH1/IDH2) genes are metabolic enzymes, which are frequently mutated in acute myeloid leukemia (AML)." (PMID 25324972, 2014). "The scientific community was further encouraged to consider this abnormality when another cancer genome project also reported the very same mutation in IDH1 and IDH2 of acute myeloid leukemia (AML) patients." (PMID 25502799, 2014). "Acquired somatic mutations of IDH1 and IDH2 have recently been reported in some types of brain tumors and a small proportion of acute myeloid leukemia (AML) cases." (PMID 22397365, 2012). "For our purposes, it is noteworthy that somatic mutations in IDH1 and IDH2 are found in several cancers – principally acute myelogenous leukemia (AML) and glioblastoma, but also cholangiocarcinomas and chondrosarcomas – and have proven to be effective therapeutic targets." (PMID 39438765, 2024). "A case study documented the detection of high-risk CH variants DNMT3A exon 23 p.R882H and isocitrate dehydrogenase 2 (IDH2) exon 4 p.R140Q at a low VAF in a patient with prostate cancer who developed acute myeloid leukemia a year later, driven by the same mutations." (PMID 40027147, 2024). "Among multiple types of cancers, IDH1 or/and IDH2 mutations have been identified, inter alia, in acute myeloid leukemia (AML), gliomas, chondrosarcoma, intrahepatic cholangiocarcinoma, thyroid carcinoma, and also rarely in prostate cancer, melanoma, and paraganglioma." (PMID 35628385, 2022). "Mutations in proto-oncogene IDH1 and IDH2, are usually found in glioma and acute myeloid leukemia (AML), resulting in a hypermethylated profile that confer a selective advantage to the mutated subpopulation of cells, in term of growth rate and stemness capability." (PMID 39086963, 2022). "Notably, AG-221 and AG-881 are in clinical trials for treatment of acute myelogenous leukemia carrying IDH2 or IDH1/2 mutations, respectively." (PMID 35831624, 2022). "Serum 2-HG in IDH1-mutated and IDH2-mutated cancers like acute myeloid leukemia is about 300 μM44." (PMID 34131130, 2021). "Enasidenib may be an important advance in treatment for patients with R/R acute myeloid leukemia associated with IDH2 mutations who are ineligible for hematopoietic stem cell transplantation." (PMID 34427990, 2021). "A recent example of this is enasidenib, an isocitrate dehydrogenase 2 (IDH2) inhibitor, which has been approved by the Food and Drug Administration (FDA) for the treatment of relapsed or refractory acute myeloid leukaemia (AML) in patients bearing IDH2 mutations." (PMID 31819196, 2020).
acute myeloid leukemia (continued). "Ward and colleagues demonstrate the mutations in isocitrate dehydrogenase 2 (IDH2), commonly found in acute myeloid leukemia (AML), abrogate the enzyme’s wild-type activity and confer to the mutant neomorphic activity that produces the oncometabolite 2-hydroxyglutarate (2-HG)." (PMID 26943899, 2016). "Interestingly, gain-of-function mutations of the enzymes responsible for 2-oxoglutarate synthesis, IDH1 and IDH2, have been associated with tumorigenesis, in particular glioblastomata and acute myeloid leukemia." (PMID 25568311, 2015). "IDH1 and IDH2 mutations widely occur in gliomas and acute myeloid leukemia, leading to the production of 2-hydroxyglutarate (2-HG), which inhibits multiple α-KG-dependent dioxygenases, including the TET family of 5-mC hydroxylases (which results in decreased 5-hmC)." (PMID 24716838, 2014). "IDH1/2 mutations are also found in acute myeloid leukemia (AML), with IDH2 mutations being more prevalent, resulting in specific clinical features and a distinct prognosis." (PMID 40075667, 2025). "Enasidenib, an oral inhibitor of mutant isocitrate dehydrogenase-2 (IDH2) protein, was approved in the United States in 2017 to treat adult patients with relapsed or refractory (R/R) acute myeloid leukemia (AML) with an IDH2 mutation." (PMID 41249771, 2025). "Bimiralisib has also been shown to have efficacy in combination with BCL2 (B-cell lymphoma 2) inhibitor venetoclax in acute myeloid leukemia (AML) with IDH2, NPM1, and FLT3 mutations in preclinical studies." (PMID 38396649, 2024). "IDH inhibitors are another type of targeted therapy that target genetic mutations in the isocitrate dehydrogenase genes (IDH1 and IDH2) in acute myeloid leukemia (AML), occurring in up to 30% of AML cases." (PMID 37374055, 2023). "Isocitrate dehydrogenase 2 (IDH2) mutations occur in more than 15% of cytogenetically normal acute myeloid leukemia (CN-AML) but comparative studies of their roles in leukemogenesis have been scarce." (PMID 36739363, 2023). "Recurrent mutations in IDH1 or IDH2 in acute myeloid leukemia (AML) are associated with increased DNA methylation, but the genome-wide patterns of this hypermethylation phenotype have not been comprehensively studied in AML samples." (PMID 34873300, 2022). "IDH2 mutation is an oncogenic event in acute myeloid leukemia (AML) due to the generation of 2-hydroxyglutarate." (PMID 35313945, 2022). "IDH1/IDH2 mutations are also present in other neoplasms, such as acute myeloid leukemia (AML), chondrosarcoma and cholangiocarcinoma." (PMID 36011350, 2022). "Allosteric inhibitors of mutant IDH1 or IDH2 induce terminal differentiation of the mutant leukemic blasts and provide durable clinical responses in approximately 40% of acute myeloid leukemia (AML) patients with the mutations." (PMID 33972549, 2021). "A number of malignancies have been found to be associated with mutations in the gene encoding isocitrate dehydrogenase 1 (IDH1) and IDH2, including acute myeloid leukemia (AML) and myeloproliferative neoplasms." (PMID 34360786, 2021). "Among its three isoforms, mutations in the IDH1 and IDH2 genes are found in the majority of low- and high-grade gliomas as well as in 20% of adults with acute myeloid leukemia (AML), and 5% of adults with myelodysplastic syndromes (MDSs)." (PMID 33673109, 2021). "Heterozygous mutations in IDH1 and IDH2 have also been detected in gliomas/glioblastomas and acute myeloid leukemia (AML)." (PMID 34790172, 2021). "IDH1 and IDH2 mutations are found in multiple tumors, including glioma and acute myeloid leukemia (AML)." (PMID 35008250, 2021). "Mutations in the IDH1 and IDH2 genes are found in multiple hematologic and solid tumors, including acute myeloid leukemia (AML) and glioma." (PMID 31028664, 2020). "Enasidenib, a first-in-class inhibitor of mutated IDH2, was approved for the treatment of acute myeloid leukemia (AML)." (PMID 32733473, 2020).